PSMD3 (proteasome 26S subunit, non-ATPase 3)
Diseases named in the same sentence as PSMD3 in open-access papers (continued):
Sharing a sentence is not in itself a finding about the gene and the disease.
urothelial bladder carcinoma (1 paper, 2023). "In urothelial bladder carcinoma, PSMD2, PSMD3, PSMD4, PSMD8, and PSMD11 genes are overexpressed." (PMID 36934426, 2023).
cancer (16 papers, 2016 to 2026). A tumor composed of atypical neoplastic, often pleomorphic cells that invade other tissues. "Altogether, mutations, amplification, or deep deletions in the genes encoding PSMD1 and PSMD3 could explain their differential expression in different types of cancers." (PMID 34572038, 2021). "Using cBioPortal to analyze multiple TCGA cancers, we previously reported that altered PSMD1 expression was associated with mutations or deep deletions in several different solid tumors, whereas PSMD3 was primarily associated with gene amplifications." (PMID 36498916, 2022). "We also previously showed that PSMD1 and PSMD3 mRNA expression are upregulated in other types of cancers compared with normal tissue, and that this often correlates with a worse prognosis." (PMID 36498916, 2022). "PSMD3, on the other hand, was found differentially expressed at the mRNA level in 18/24 (75%) TCGA cancers." (PMID 34572038, 2021). "It was noted that three of the four genes, i.e., MZB1, DERL3, and PSMD3, were more highly expressed in cancer tissues than in adjacent normal lung tissues." (PMID 34212001, 2021). "We propose that PSMD1 and PSMD3, both subunits of the 19S regulatory complex of the 26S proteasome, are proteins worthy of further investigation for cancer prognosis and therapy." (PMID 34572038, 2021). "Altogether, these data indicate that high expression levels of PSMD1 and PSMD3 mRNA correlate with worse outcomes in multiple different cancers, with the exception of patients with DLBCL, STAD, and THYM." (PMID 34572038, 2021). "Our analysis revealed that differential expression of PSMD1 and PSMD3 is correlated with worse OS in several different cancer types." (PMID 34572038, 2021). "Our data implicate PSMD1 and PSMD3 as potential targets for combination therapies in myeloid malignancies and possibly other cancers." (PMID 33712704, 2021). "In the present study, we used publically available databases to assess the effects of altered PSMD1 and PSMD3 mRNA and protein expression on disease progression and OS for multiple different cancers." (PMID 34572038, 2021). "Altogether, these data confirm that PSMD1 and PSMD3 mRNA and protein are differentially expressed in multiple types of human cancers, similar to our recent findings in CML disease progression and TKI resistance." (PMID 34572038, 2021). "For the cancers demonstrating significant differences in OS, we next associated PSMD1 and PSMD3 mRNA expression with clinicopathological characteristics using UALCAN." (PMID 34572038, 2021). "Ultimately, we highlight PSMD1 and PSMD3 as potential therapeutic targets for the development of novel proteasome inhibitors to treat cancer patients with less toxicity." (PMID 34572038, 2021). "Recently, PSMD3 was reported to participate in several human cancers by targeting various factors." (PMID 37337223, 2023). "Bortezomib and carfilzomib are proteasome inhibitors approved for cancer therapy, whereas PSMD3 encodes one of the non-ATPase subunits of the 19S regulatory lid." (PMID 37965141, 2023). "Similarly, we found that PSMD1 and PSMD3 mRNA expression is upregulated in multiple cancer types compared with normal tissue." (PMID 36498916, 2022). "The observation that PSMD1 and PSMD3 are upregulated in multiple different cancer types suggested that they may also play a role in outcomes." (PMID 34572038, 2021). "The post-translational modifications of PSMD1 or PSMD3 could provide a starting point for targeting these proteins in cancer therapy." (PMID 34572038, 2021). "However, the other subunits of proteasome, such as PSMD3, PSMC2, and PSMD4, were upregulated in several cancers and associated with prognosis." (PMID 34239933, 2021). "We next sought to determine whether expression of PSMD1 or PSMD3 correlates with OS in various cancers." (PMID 34572038, 2021). "PSMD3 is widely expressed in most tissues and defined as an oncogene in various cancers." (PMID 34804978, 2021).
cancer (continued). "PSMD1, PSMD3, and the signaling pathways regulated by them, could be novel molecular targets for improved cancer therapy." (PMID 34572038, 2021). "Altogether, our data suggest that PSMD1 and PSMD3 may be novel putative targets for cancer prognosis and therapy that are worthy of future investigation." (PMID 34572038, 2021). "In the present study, we comprehensively analyzed the expression and prognostic value of PSMD1 and PSMD3 across multiple cancer types using data from The Cancer Genome Atlas (TCGA) and the Clinical Proteomic Tumor Analysis Consortium (CPTAC), comparing expression with OS." (PMID 34572038, 2021). "Thus, there appears to be tissue-specific differences on the phenotype resulting from altered expression of PSMD1 or PSMD3 in different cancer types." (PMID 34572038, 2021). "Additionally, PSMD3 from our CARBO model was identified as differentially expressed in human cancer cell lines that were sensitive or resistant to the EGFR inhibitor lapatanib." (PMID 26892349, 2016). "Altogether, these findings suggest that PSMD1 and PSMD3 mRNA expression could serve as novel prognostic biomarkers for cancers affecting multiple different tissue types, especially for patients with KICH who are progressing from stage 3 to stage 4 of the disease." (PMID 34572038, 2021). "Ultimately, our analysis demonstrated that PSMD1 and PSMD3 mRNA and protein were markedly upregulated in numerous different cancers, which correlated with a worse OS, indicating they may serve as novel prognostic biomarkers in cancer diagnosis and therapy response." (PMID 34572038, 2021). "Additionally, PSMD1 and PSMD3 may be novel prognostic biomarkers for cancers affecting multiple different tissue types." (PMID 34572038, 2021). "In our analysis, however, some of the cancer types showed a similar phenotype, demonstrating decreased OS with decreased PSMD1 or PSMD3 expression." (PMID 34572038, 2021). "Future studies will determine the mechanism by which PSMD1 or PSMD3 are upregulated in CML and other types of cancers, and will interrogate their potential as novel therapeutic targets." (PMID 34572038, 2021). "The broad pan-cancer HER2 amplicon shared by at least 60% of HER2A tumors spans 532 kb, contains 13 additional genes from CDK12 to PSMD3, and is narrower compared to breast." (PMID 29382369, 2018). "Proteasome 26S subunit, non-ATPase 3 (PSMD3) has been reported to participate in various human cancers." (PMID 37337223, 2023). "Based on our recent data in CML and other types of cancers, we hypothesized that PSMD1 and PSMD3 mRNA expression would be upregulated in AML versus normal mononuclear cells (MNCs), and that high expression would correlate with a worse OS." (PMID 36498916, 2022). "Alternatively, during oncogenesis as cancer cells rapidly divide, the increase in gene expression could be due to gene amplifications, where more copies of PSMD1 and PSMD3 are erroneously introduced during replication." (PMID 34572038, 2021). "Altogether, our data suggest a role for PSMD1, PSMD3, and STAT3 in regulating NF-κB expression and activity in CML and TKI resistance, and implicate them as potential targets for the treatment of hematologic malignancies and possibly other forms of cancer." (PMID 33712704, 2021). "As knockdown of TAD anchor non-oncogenes PSMD3 led to activation of its partner boundary oncogene CDK12, RNA mutation of the non-oncogene could be a potential mechanism that underlies cancer driver gene activation." (PMID 40051047, 2025). "In addition, studies have shown that PGAP3, GRB7, STARD3, and PSMD3 are significantly positively correlated with STAT3 in TCGA cancers; however, reports on these are lacking." (PMID 36977736, 2023).
cancer (continued). "Therefore, we hypothesized that PSMD1 and PSMD3 are potential targets for anti-cancer therapeutics and that their relevance stretches beyond CML to other types of cancers." (PMID 34572038, 2021).
tumor (6 papers, 2019 to 2025). "Our outcomes displayed that the tumor growth rate in the PSMD3 group was greatly faster than Ctrl, whereas that in the PSMD3 + YM155 group was slower compared to the PSMD3 group." (PMID 37337223, 2023). "Knockdown of PSMD3 resulted in a significant reduction of subcutaneous tumor size by over threefold compared with shNT tumors." (PMID 33712704, 2021). "Group 1 included patients with PSMD3 at a higher level in normal (N) tissues than in tumor (T) tissues (N > T, 23/176, 13%)." (PMID 31013812, 2019). "High PSMD3 expression was significantly associated with HER2+ BC subtypes (p < 0.001), tumor size (p < 0.001), and clinical stage (p = 0.036)." (PMID 31013812, 2019). "PSMD3 was upregulated in BC cell lines and tumor tissues were compared to normal breast cells and tissues." (PMID 31013812, 2019). "Cytoplasmic and nuclear immunostaining of PSMD3 was markedly detected in tumor tissues compared with normal tissues, which have low PSMD3 immunostaining." (PMID 31013812, 2019). "Group 2 included patients with a higher PSMD3 level in tumors tissues than in normal tissues (T > N, 153/176, 87%); the results indicated the upregulation of PSMD3 in tumor tissues." (PMID 31013812, 2019). "PCR amplification curves generated from tumor samples were shifted forward (red lines) relative to curves generated from normal tissues (green lines), indicating relatively higher PSMD3 expression in tumor tissues." (PMID 31013812, 2019). "High expression level of PSMD3 was associated with HER2 expression (p < 0.001), tumor size (p < 0.001), and clinical stage (p = 0.036)." (PMID 31013812, 2019). "Next, we examined the level of PSMD3 mRNA in pairs of tumor and adjacent normal breast tissue samples using quantitative real-time PCR (n = 176)." (PMID 31013812, 2019). "Tumor xenograft model was used to evaluate the function of PSMD3 on tumor growth." (PMID 37337223, 2023). "Finally, we performed IHC staining in nude tumor tissues and found that PSMD3 staining was much weaker in the shPSMD3 group than in the shCtrl group." (PMID 37337223, 2023). "In the present study, we analyzed PSMD1 and PSMD3 mRNA and protein expression in cancerous tissue versus normal controls using data from The Cancer Genome Atlas (TCGA) and the Clinical Proteomic Tumor Analysis Consortium (CPTAC), comparing expression with overall survival." (PMID 34572038, 2021). "The highest level of PSMD3 was detected in tumor tissues with HER2+ expression." (PMID 31013812, 2019). "However, according to the TCGA database, high PSMD3 levels have significant differences with tumor size, stage of the disease, and importantly, HER2 status." (PMID 31013812, 2019). "PSMD3 immunostaining was detected in the cytoplasm and nucleus of BC tumor tissues." (PMID 31013812, 2019). "We further confirmed PSMD3 expression at the mRNA level using pairs of breast tissue samples, normal (N) versus tumor (T), by reverse transcription polymerase chain reaction (RT-PCR); PSMD3 was upregulated in 7 out of 10 HER2+ tumor tissues, compared to the relative normal tissues." (PMID 31013812, 2019). "Furthermore, animal experiments showed that the ILF3 inhibitor YM155 could suppress tumor growth with the presence of PSMD3." (PMID 37337223, 2023). "PSMD3 overexpression significantly promoted tumor growth, while YM155 considerably slowed tumor growth." (PMID 37337223, 2023). "We also performed IHC staining in nude tumor tissues and found PSMD3 and ILF3 staining were much stronger in the PSMD3 group than Ctrl group, while these in the PSMD3 + YM155 group were slighter than PSMD3 group." (PMID 37337223, 2023). "The protein levels of PSMD3, ILF3 and pEGFR significantly grew in tumor tissues of the PSMD3 group compared to Ctrl group, which greatly decreased in PSMD3 + YM155 group compared to PSMD3 group." (PMID 37337223, 2023).
tumor (continued). "The sixth HER2+ cell lines, HER2+ tumor tissues, and patients with HER2+ from the Oncomine and TCGA databases showed significantly higher levels of PSMD3 compared to normal breast tissue or to other BC subtypes." (PMID 31013812, 2019). "IHC results revealed that PSMD3 was obviously investigated in tumor tissues compared to normal ones." (PMID 37337223, 2023). "In addition, PSMD3 can regulate ILF3 protein stability and facilitate the ubiquitination of endogenous ILF3 in LC, which exerted an oncogenic effect on tumor growth and proliferation." (PMID 37337223, 2023). "Co-silencing of PSMD3 and HER2 gave an additive effect for inhibiting the viability and cell proliferation of the tumor cells rather than a single treatment in the KPL4 cell line." (PMID 31013812, 2019).
PSMD3 also shares sentences with these, for which no sentence is quoted: asthma (4 papers); cervical cancer (2); COVID-19 (2); infection (2); ovarian carcinoma (2); Alzheimer disease (1); bladder cancer (1); breast-invasive carcinoma (1); childhood onset asthma (1); chronic rhinitis (1); Epstein-Barr virus infection (1); head and neck cancer (1); hematologic malignancies (1); Huntington disease (1); Hypertension (1); Infertility (1); kidney renal cancer (1); liver cancer (1); melanoma (1); myelodysplastic syndrome (1); ovarian serous carcinoma (1); serous ovarian cancer (1); Stroke (1); triple-negative breast carcinoma (1); viral pneumonia (1).